PTPRS (protein tyrosine phosphatase receptor type S)
Diseases named in the same sentence as PTPRS in open-access papers (continued):
Sharing a sentence is not in itself a finding about the gene and the disease.
lung adenocarcinoma (1 paper, 2022). A carcinoma that arises from the lung and is characterized by the presence of malignant glandular epithelial cells. "We found that TGFB1, ENG, TGM2, TBXA2R, HSPG2, and PTPRS were significantly upregulated in lung adenocarcinoma cells." (PMID 36249427, 2022).
lymph node metastasis (1 paper, 2022). "PTPRS was associated with serum albumin (P = 0.028), lymph node metastasis (P = 0.038), and the survival time of patients (P = 0.011)." (PMID 35991009, 2022).
neuroblastoma (1 paper, 2021). Neuroblastoma (NB) is the most common solid, extracranial childhood tumor. "Distinctly to PTPRD, the related PTPRS enzyme is highly expressed in neuroblastoma cells." (PMID 34957126, 2021). "Whether PTPRS or PTPRF may directly regulate the tyrosine phosphorylation of Trk receptors or other specific substrates in neuroblastoma cells, deserves experimental analysis." (PMID 34957126, 2021).
NK-cell enteropathy (1 paper, 2025). "Diseases associated with PTPRS include NK-cell enteropathy and papillary tumors of the pineal region; the related pathways are signaling by NTRKs and protein–protein interactions at synapses." (PMID 40430440, 2025).
pineal tumors (1 paper, 2022). "Nevertheless, in this report, we describe two pathology-confirmed PTPRs in which presurgical proton MR spectroscopy demonstrated extremely high myoinositol, a pattern which drastically differs from that of other pineal tumors." (PMID 35741688, 2022).
ulcerative colitis (1 paper, 2025). An inflammatory bowel disease involving the mucosal surface of the large intestine and rectum. "There is no literature implicating PTPRS in CKD progression but it has been implicated in ulcerative colitis activity and was highly expressed in small arteries of people with CKD." (PMID 40342947, 2025).
viral infection (1 paper, 2024). "Six genes were closely associated with viral infection, namely, LY6E, receptor-type tyrosine-protein phosphatase S (PTPRS), neurogenic locus notch homolog protein 3 (NOTCH3), tripartite motif containing 56 (TRIM56), ring finger protein 135 (RNF135), and growth arrest-specific 6 (GAS6)." (PMID 38169284, 2024).
cancer (17 papers, 2010 to 2025). A tumor composed of atypical neoplastic, often pleomorphic cells that invade other tissues. "Diagnostic and prognostic value of serum PTPRS levels should be investigated further in other cancer patients." (PMID 35991009, 2022). "PTPRs were previously regarded as tumoral suppressors and are inactivated due to genetic mutations in human cancer." (PMID 31829261, 2019). "Mutation or deletion of PTPRS was detected in several human cancers including head and neck squamous-cell carcinoma, colorectal cancer, malignant melanoma, and cholangiocarcinoma." (PMID 29558404, 2018). "Loss of PTPRS function through mutation or deletion has been shown to increase TKI resistance in multiple human preclinical cancer models and has been linked with worse overall survival and more rapid disease progression in patients with EGFR-driven lung cancer." (PMID 38049664, 2024). "The present study has identified 4 cancer driver genes (PTCH1, DNMT3A, PTPRS, JAK2) that rank highest in responders and are linked to enhanced survival in the validation cohort, either as individual markers or as part of a grouped marker panel." (PMID 38951894, 2024). "The genetic and epigenetic alterations of the phosphatases lead to aberrant cell signaling, which suggests that the PTPRs are critical components in the carcinogenesis of several cancers such as CRCs36,37." (PMID 35562390, 2022). "Recently, studies have revealed vital roles of PTPRS in immune-mediated intestinal inflammation, autophagy and progression of various types of cancers." (PMID 33163494, 2020). "In gastric tissue, the expression of PTPN4, PTPRA, and PTPRS were increased in cancer tissue compared with normal tissue." (PMID 30126387, 2018). "The possible role of PTPRS in tumor progression was studied in several types of cancer." (PMID 35991009, 2022). "Recently, PTPRS was reported as tumor suppressor in a variety of cancers." (PMID 29558404, 2018). "In addition, STAT3 was another downstream target of PTPRS in cancer progression." (PMID 33163494, 2020). "GZMB can inhibit the T cell proliferation, PTPRS can inhibit the production of interferon, and CLIC3 takes part in the angiogenesis and increases the invasiveness of cancer cells." (PMID 40755770, 2025). "PTPRS is an important gene in regulating the RAS/ERK pathway, although their functional role in cancer is much less understood than their counterpart protein tyrosine kinases." (PMID 37175550, 2023). "LDHB, PTPRS, UHRF1, and TUBB3 were proposed as universal prognostic and malignancy markers across many cancer types." (PMID 36900348, 2023). "Protein tyrosine phosphatase receptor type S (PTPRS) was highly expressed in OV cancer cells and correlated with MYC/E2F targets, indicating that pleiotrophin (PTN) was secreted by fibroblasts binding to its receptor to promote the cancer cell growth." (PMID 34676217, 2021).
tumor (15 papers, 2008 to 2025). "Using an integrated approach to compare gene mutations with global gene expression in our 468 human CRC tumor collection, we showed that mutations in PTPRS highly correlated with an increase in a validated RAS pathway activity signature." (PMID 31827720, 2019). "PTPRS is significant in that it can distinguish CSCs from normal brain cells using single-cell RNA sequencing and is one of seven genes whose mRNA expression is associated with tumor grade, with GBM exhibiting the highest levels." (PMID 39123468, 2024). "The cumulative results of predictors and structural protein indicate that selected tumor-associated PTPRS mutation is a strong candidate to be associated with the development of non-RET MTC, but mutational screening of this gene in these familial cases should be clarified." (PMID 37175550, 2023). "We recently discovered that protein tyrosine phosphatase receptor S (PTPRS) was the most frequently mutated gene (~10%) in the family of protein tyrosine phosphatases in our CRC tumor collection (n = 468); similar results were reported for the Dana Farber CRC database." (PMID 31827720, 2019). "Since PTPRS was reported to have a tumor suppressor-like role, we postulated that the somatic mutations of PTPRS, if functional, might be inactivating mutations, which could mediate RAS/ERK pathway activation, which is a driver of tumorigenesis." (PMID 29915291, 2018). "Since our data showed that loss of PTPRS increased the phosphorylation of ERK in tumor cells driven by both mutant KRAS as well as wild-type KRAS, we sought to further confirm the effects of PTPRS knockout (KO) on CRC cells, independent of KRAS mutation status." (PMID 29915291, 2018). "Although oncogenic PTPRs are attractive molecules for the development of targeted therapies, the development of PTPR inhibitors remains challenging due to the high level of conservation in the active site of tumor suppressor and oncogenic PTPRs." (PMID 39234247, 2024). "Other regulators of tumor biology, including PTPRS, CSPG4, SPRED1, CD59, and PROCR, were all downregulated upon CBX3 knockdown." (PMID 39545414, 2024). "The most significantly downregulated gene in LS174T-Fx-R cells was protein tyrosine phosphatase receptor S (PTPRS), a tumor suppressor gene known to mediate cell migration and invasion by downregulation of epithelial-mesenchymal transition." (PMID 36230735, 2022). "Along with the high levels of PTPRS and dendritic nature of the tumor cells, these findings suggest a possible pre-inflammatory context of this disease, in which BPDCN features nonactivated pDCs." (PMID 31811114, 2019). "Down-regulation of PTPRS was observed in HCC samples compared with non-tumor liver samples, and low expression of PTPRS was also observed in most of HCC cell lines." (PMID 29558404, 2018). "PTPRS has also been shown to play a role in ulcerative colitis, intestine epithelial permeability, autophagy regulation, and tumor suppression." (PMID 29915291, 2018). "Interestingly, we found that PTPRS mutations occur in 10% of CRC tumors in our database and also in the Dana Farber CRC tumor database." (PMID 35326598, 2022). "PTPRS has been shown to have a role in neural system biology, spinal injury repair, intestinal permeability, ulcerative colitis, autophagy and tumor suppression." (PMID 31827720, 2019). "PTPRS promoter methylation was detected in HCC tumor samples and in HCC tumor cell lines." (PMID 31827720, 2019). "Also, in HCC, high PTPRS expression in the tumor was associated with non-aggressive tumor characteristics and a low risk of postoperative recurrence." (PMID 35991009, 2022). "Knockdown of PTPRS in MPNST cell lines increased migration/invasion and EMT processes were induced with increased N-cadherin and decreased E-cadherin, which indicated PTPRS may serve as a tumor suppressor in MPNST." (PMID 33163494, 2020).
inflammation (1 paper, 2018). Aberrant reaction of the microcirculation characterized by movement of fluid and leukocytes from the blood into extravascular tissues. "Accordingly, specific ablation of the inhibitory protein tyrosine phosphatase receptor type S (PTPRS) on pDCs was associated with the development of mild intestinal inflammation in mice." (PMID 30410494, 2018).
neurodegenerative disease (1 paper, 2024). A disorder of the central nervous system characterized by gradual and progressive loss of neural tissue and neurologic function. "Cis-eQTL analysis of the PTPRS gene region identified a polymorphism, rs10415488, that reached locus-wide significance in the BRAINEAC cohort, composed of 134 brains free of neurodegenerative diseases." (PMID 38926456, 2024).
PTPRS also shares sentences with these, for which no sentence is quoted: autism spectrum disorder (2 papers); cholangiocarcinoma (2); head and neck squamous cell carcinoma (2); metabolic disease (2); Obesity (2); angiosarcoma (1); autism (1); bipolar disorder (1); brain disorder (1); brain injury (1); breast carcinoma (1); C. perfringens infection (1); CNS tumors (1); colitis (1); colon cancer (1); diabetes (1); dystroglycanopathies (1); esophageal squamous cell carcinoma (1); hamartoma (1); Kidney Cyst (1); multiple sclerosis (1); neurodevelopmental disorder (1); Neurological Disorders (1); neuropathies (1); ovarian carcinoma (1); panic disorder (1); rectum adenocarcinoma (1); restless leg syndrome (1); schizophrenia (1); tumor of the cerebellum (1).
A further 1 disease shares a sentence with PTPRS in 1 paper.